MFN1 (mitofusin 1)
Diseases named in the same sentence as MFN1 in open-access papers (continued):
Sharing a sentence is not in itself a finding about the gene and the disease.
neuropathy (1 paper, 2025). A disorder affecting the nervous system that manifests with pain, tingling, numbness, and/or muscle weakness. "As well as considering pharmacological approaches, future screens may also seek genetic modifiers of the phenotype, including knockdown of the Mfn2 paralogue Mfn1, which has been shown in some contexts to compensate for at least some neuropathy-causing mitofusin 2 mutations." (PMID 40759924, 2025).
non-small cell lung carcinoma (1 paper, 2020). A group of at least three distinct histological types of lung cancer, including non-small cell squamous cell carcinoma, adenocarcinoma, and large cell carcinoma. "Mitochondrial EGFR also induces mitochondrial fission through inhibition of MFN1 and enhances energy production and cell motility to promote metastasis of non-small-cell lung cancer." (PMID 33019722, 2020).
nonalcoholic fatty liver disease (1 paper, 2025). "In pulmonary inflammation caused by nonalcoholic fatty liver disease, MFN1 expression is significantly reduced; however, exercise training can restore MFN1 levels and reestablish pulmonary mitochondrial homeostasis." (PMID 40177356, 2025).
normal tension glaucoma (1 paper, 2009). "Common variants of OPTN, PARL, MFN1 and MFN2 should be analysed in other cohorts to confirm their involvement in normal tension glaucoma." (PMID 19754948, 2009).
optic atrophy type 1 (1 paper, 2022). "The dynamics of mitochondrial morphology are mediated by mitofusin-1(Mfn1), Mfn2, and optic atrophy type 1." (PMID 36212689, 2022).
periodontal disease (1 paper, 2025). "In conditions such as periodontal disease, oxidative stress, and inflammation are frequent, MFN1 along MFN2 assist in preventing cell damage by managing mitochondrial integrity." (PMID 39896143, 2025). "The therapeutic possibility of targeting MFN1 along MFN2 for periodontal disease is ascribed to their purpose in mitochondrial fusion, control of inflammation, and cellular resilience." (PMID 39896143, 2025). "Studies were selected depending on inclusion criteria based on the roles of MFN2 and MFN1 in periodontal disease and health." (PMID 39896143, 2025). "The aim of the current study is to comprehensively review including evaluate the roles of MFN2 and MFN1 in the pathogenesis as well as the progression of periodontal disease, foregrounding their effect on mitochondrial integrity, inflammatory pathways, and oxidative stress." (PMID 39896143, 2025). "Speaking about how MFN1 along MFN2 work in periodontal disease could give new intuition into pathogenesis as well as possible treatment approaches as they are important for preserving cellular stress, regulating inflammatory pathways, and mitochondrial integrity." (PMID 39896143, 2025). "The study of MFN1 along with MFN2 as a therapeutic quarry, offers a promising perception of periodontal disease care." (PMID 39896143, 2025). "In conclusion, this comprehensive review highlights the critical roles of MFN1 and MFN2 in mitochondrial dynamics, inflammation regulation, and cell survival within periodontal disease." (PMID 39896143, 2025). "MFN1 among MFN2 significantly mitigates oxidative stress as well as inflammation and is censorious in periodontal disease." (PMID 39896143, 2025). "Key findings indicate that MFN1 and MFN2 levels are often reduced in periodontal disease conditions, correlating with increased oxidative stress, inflammation, and mitochondrial dysfunction." (PMID 39896143, 2025). "The included studies in this review provide a comprehensive look at the roles of MFN1 and MFN2 in periodontal disease, utilizing a variety of models, including in vitro and in vivo approaches." (PMID 39896143, 2025). "This comprehensive review aims to evaluate the part of MFN1 along MFN2 in the pathogenesis, including the progression of periodontal disease, focusing their effect on oxidative stress, inflammatory pathways, and mitochondrial integrity." (PMID 39896143, 2025). "MFN1 along MFN2 are both important for managing oxidative stress, this is a crucial grantor to the evolution of periodontal disease." (PMID 39896143, 2025). "The included studies underscore the significant role that MFN1 and MFN2 play in mitochondrial dynamics and their implications in periodontal disease." (PMID 39896143, 2025). "The current comprehensive review shows the important roles of MFN1 along with MFN2 in inflammation regulation, cell survival, and mitochondrial dynamics within periodontal disease." (PMID 39896143, 2025). "MFN1 and MFN2 levels were monitored in order to shed light on the possible role of mitochondria-endoplasmic reticulum interaction genes in the etiology of periodontal disease." (PMID 39896143, 2025). "MFN1 along with MFN2 modulates inflammatory signaling and controls ROS generation, so influencing the host immunological reaction to pathogens and may influence the course of periodontal disease and severity." (PMID 39896143, 2025). "The purpose of MFN1, along with MFN2 encompasses not just mitochondrial integrity and the regulation of inflammation, a crucial element in periodontal disease." (PMID 39896143, 2025).
prion disease (1 paper, 2019). A transmissible disease that is caused by a protein that is able to induce abnormal folding of normal cellular proteins, leading to characteristic spongiform brain changes, which are associated with neuronal loss without an inflammatory response. "To search for other mitochondrial fusion proteins involved in mitochondrial network fragmentation and mitochondrial dysfunction in prion diseases, in this study we investigated the expression of mitochondrial fusion-regulating proteins, OPA1, MFN1, and MFN2." (PMID 31551424, 2019).
rheumatoid arthritis (1 paper, 2023). A chronic, systemic autoimmune disorder characterized by inflammation in the synovial membranes and articular surfaces. "Leflunomide is also known as an anti-inflammatory drug used against rheumatoid arthritis, which increases mitochondrial elongation by depleting the pyrimidine pool and altering MFN1/2 protein levels through loss of pyrimidine synthesis." (PMID 36939338, 2023).
sarcoma (1 paper, 2025). A usually aggressive malignant neoplasm of the soft tissue or bone. "Although these results exclude the role of MFN1 in sarcoma multidrug resistance, further research might elucidate its potential involvement in regulating selective resistance to topotecan." (PMID 39643272, 2025).
scrapie (1 paper, 2023). A fatal disease of the nervous system in sheep and goats, characterized by pruritus, debility, and locomotor incoordination. "In scrapie-infected mice, an imbalance in mitochondrial fusion and fission proteins such as Mfn1, Fis1, Mfn2, and Dlp1 was observed." (PMID 37569615, 2023).
steatosis (1 paper, 2023). Increased lipid within the cytoplasm of cells. "Mfn1, Mfn2, and Opa1 mRNA expression in steatosis LO2 cells was also significantly lower, while the mRNA expression levels of Fis1 and Drp1 were much higher than those in the control (p < 0.01) and the taurine groups (p < 0.01)." (PMID 37373507, 2023).
Stroke (1 paper, 2025). Sudden impairment of blood flow to a part of the brain due to occlusion or rupture of an artery to the brain. "The effects of silencing ATF3 on neurological injury, infarction, adenosine triphosphate (ATP), nicotinamide adenine dinucleotide (NAD+), mitofusin 1 (MFN1) and MFN2 were evaluated in stroke rats." (PMID 40621504, 2025).
tauopathy (1 paper, 2025). Neurodegenerative disorders involving deposition of abnormal tau protein isoforms (tau proteins) in neurons and glial cells in the brain. "In this study, we observed an upregulation of the mitochondrial fission protein DRP1 in the SH‐SY5Y tauopathy model, while the levels of fusion proteins MFN1, MFN2, and OPA1 remained unchanged." (PMID 40344412, 2025).
thyroid tumor (1 paper, 2015). A benign or malignant neoplasm affecting the thyroid gland. "The expression of mitochondrial fusion (Opa1, Mfn1 and Mfn2) and fission (Drp1 and Fis1) proteins were evaluated by immunohistochemistry (IHC) in a series of 88 human thyroid tumors." (PMID 25822260, 2015).
tongue cancer (1 paper, 2019). A malignant neoplasm affecting the tongue. "Differential expression profiling of the tongue cancer cohort triaged based on the stage, pathology identified multiple candidate markers; JAM2, SMURF1, LY6E, MFN1 and SUPT16H." (PMID 31310629, 2019).
type 2 diabetic (1 paper, 2025). "Similarly, in type 2 diabetic rat models, high-glucose or high-fat stimulation induces pathological cardiac fission, manifested at the molecular level by significant downregulation of Mfn1 expression and enhanced post-translational modifications of the fission-related protein Drp1." (PMID 40804395, 2025).
α-synucleinopathy (1 paper, 2021). "Given the alterations in Drp1 levels in the TgA53TG2-3 models, we examined whether the expression of MFN1, OPA1, and Fis1 was altered as a function of α-synucleinopathy." (PMID 33924585, 2021).
cancer (40 papers, 2013 to 2026). A tumor composed of atypical neoplastic, often pleomorphic cells that invade other tissues. "Increased fission or mitochondrial fragmentation due to high expression and activity of Drp1 and decreased fusion due to loss of Mfn1 activity are often linked to cancer cell migration, invasiveness, and metastasis." (PMID 28373964, 2017). "Higher expression of Mfn1 and Mfn2 has been linked with cancer cell proliferation, enhanced cell survival and invasion." (PMID 28473727, 2017). "Given that Mfn1 depletion has been associated with invasive cancer types, it seems reasonable to hypothesize that tumors may have developed the ability to resist to apoptosis, despite their frequently fragmented mitochondrial morphology." (PMID 28589083, 2017). "It indicates its promising therapeutic potential for cancer, supported by the observations that Mfn1 and Mfn2 expression in several different types of cancer was reduced." (PMID 41531728, 2026). "Due to disruptions in fusion and fission processes, regulated by proteins like Drp1 and MFN1/2, cancer cells often display fragmented mitochondria, which are linked to increased motility, metastasis, and tumor progression." (PMID 40724998, 2025). "In drug-resistant cancer cells, mitochondrial fusion is markedly enhanced, a process primarily underpinned by upregulated expression of mitofusin 1 and 2 (Mfn1/2)." (PMID 41573644, 2025). "HCC patients with high Drp1 expression, low Mfn1 expression or a high ratio of Drp1:Mfn1 had a significantly lower overall survival rate than those with a low Drp1:Mfn1 ratio, suggesting mitochondrial dynamics are potential cancer biomarkers." (PMID 37508561, 2023). "It has been reported that mitochondrial fission is frequently increased in cancer cells due to the downregulation of the mitofusin proteins including Mfn1, Mfn2, and Opa1 and/or the upregulation of Drp1." (PMID 35582383, 2021). "Glycolysis-additive cancers include lung, gastric, breast, glioma, colon, neuroblastoma, ovarian, pancreatic, and melanoma with high levels of Drp1 and low levels of Mfn1/2 proteins." (PMID 34868997, 2021). "As a component of the outer membrane of mitochondria, MFN1/MFN2 can participate in cancer metastasis and cellular reprogramming of cancer stem cells." (PMID 33479369, 2021). "All of these studies show that the mitochondrial fusion protein Mfn1/2 can stimulate the mitochondrial biogenesis pathway and maintain mitochondrial activity in paclitaxel-resistant cancer cells." (PMID 34868997, 2021). "High expression of Mfn1, Mfn2 and OPA1 has also been linked to cancer cell proliferation, survival and invasion, while their inhibition blocks cell growth and triggers apoptosis of different cancer cells." (PMID 32244541, 2020). "Hypoxia had a nominal effect on protein expression in the cancer cells but significantly increased both fusion and fission proteins (MFN1 and DRP1, respectively) in the benign MOSE-E cells (p<0.05)." (PMID 33520711, 2020). "Some other cancer cells are characterized by either a decrease or an increase in Mfn1/2 and Fis1 expression levels, respectively." (PMID 28484497, 2017). "As observed in ES cells, lung, gastric, breast, glioblastoma, colorectal, neuroblastoma, ovarian, pancreatic, and melanoma cancer cells display high levels of Drp1 and low amounts of Mfn1/2 gene expression." (PMID 28484497, 2017). "Imbalance in expression of fission controlling protein dynamin-related protein 1 (Drp1) and fusion controlling protein Mfn1 (mitofusin 1) is observed in different cancers." (PMID 28373964, 2017). "Accordingly, inhibition of Drp1 expression or overexpression of Mfn1/2 results in a marked reduction of cancer cell proliferation and an increase in spontaneous apoptosis." (PMID 28484497, 2017).
cancer (continued). "A study examining NSCLC patient tissue has identified an alternatively spliced isoform of Mfn1 that has upregulated expression at the mRNA level that would limit apoptotic action in these cancer cells if protein expression of Mfn1 matched mRNA expression." (PMID 24688727, 2013). "Furthermore, EGFR’s interaction with mitochondrial proteins such as Mfn1 disrupts mitochondrial fusion, further supporting its role in cancer progression." (PMID 41145430, 2025). "Furthermore, reversal of mitochondrial fragmentation by FUNDC2 knockdown reduces tumor energy level, reprograms cancer metabolism, and suppresses primary liver tumors in an MFN1-dependent manner in vivo." (PMID 35710796, 2022). "Importantly, tumor invasion is suppressed when Mfn1 is silenced, further supporting a role of mitochondrial fission/fusion dynamics in cancer cell migration." (PMID 28589083, 2017). "Hence, a possible role of MFN1 editing might also be attributed in context of cancer drug resistance, which will be interesting to elucidate in future studies." (PMID 40813454, 2025). "To explore the hypothesis that dysregulated mitochondrial dynamics may impact drug sensitivity, we began by examining the alteration status of six canonical dynamics-regulating genes - OPA1, MFN1, MFN2, FIS1, MFF, and DNM1L (which encodes Drp1)—in human cancers." (PMID 29700304, 2018). "Five core genes (ACAT1, PACS2, VDAC1, MFN1, and ATAD3A) playing critical roles in cancer were identified in this study." (PMID 36902617, 2023). "In contrast to mitochondrial fusion molecules, MFN1 and MFN2 exhibit tumor-suppressing roles in cancer, and deletion of MFN1/2 promotes tumor growth and malignancy, whereas overexpression of MFN2 results in significant tumor reduction in vitro and in vivo." (PMID 36831455, 2023). "One of the most characteristic features of cancer cells is their ability to evade apoptosis, and pro-oncogenic alterations in the MEK/ERK signalling pathway lead to Mfn-1 phosphorylation, thereby preventing apoptosis." (PMID 37091853, 2023). "Having observed little MFN-1 modulation in response to DxR, MFN-2 was selected to inhibit mitochondrial fusion and OXPHOS, both of which have roles in chemo-resistant cancers." (PMID 33204855, 2020). "In particular, reduced protein expression levels of Mfn1, Mfn2, and Opa1 and high levels of Fis1 and DLP1/ Drp1 were observed in certain cancer conditions." (PMID 28402939, 2017). "Our results suggest that ERRα elevated Mfn-1 and Mfn-2 to induce EMT, resulting in cancer cell migration." (PMID 27966445, 2017). "In line with upregulated Drp1 and downregulated Mfn1, the mitochondria were smaller or more fragmented in MDA-MB-231 cancer cells." (PMID 27746856, 2016). "Because also mitochondrial fusion genes appear to be amplified in the same cancers, we wished to investigate whether levels of the three fusion mediators OPA1, MFN1 and MFN2 were upregulated across cancer types." (PMID 35279198, 2022). "Consistent with our present findings of MIEF2 in OC, increased expressions of mitochondrial dynamic proteins such as DRP1 (dynamin related protein 1), mitofusin 1 (MFN1) and mitofusin 2 (MFN2) have also been reported in human cancers of liver, lung, colon and breast." (PMID 33317572, 2020). "It has been reported that MFN1 gene expression was decreased in animals with cancer cachexia, although no consensus has been established for MFN2 in the same context." (PMID 31466311, 2019). "As observed in the case of tongue, genes associated with overall cohort, IL1RAP, ANO1, RYK, AP2M1, MFN1 and PSMD2 were significant prognosticators only in the late stage not in early cancers." (PMID 31310629, 2019). "However, in these cell lines, MFN1/2 immunoprecipitation did not reveal a convincing physical interaction with myoferlin suggesting an interaction specific to cancer cells." (PMID 32575867, 2020).
cancer (continued). "In contrast, IMQ decreased the expression of mitochondrial fusion marker Mfn1 in BCC and AGS control cells but not in Mcl-1-overexpressing cancer cells." (PMID 39272918, 2024).